IL2RB (interleukin 2 receptor subunit beta)
Diseases named in the same sentence as IL2RB in open-access papers (continued):
Sharing a sentence is not in itself a finding about the gene and the disease.
tumor (103 papers, 2008 to 2026). "TTSM cells represent a distinct population of tumor‐specific CD8+ T cells within TdLN that are characterized by the expression of canonical TCM‐associated markers, including IL‐7Ra (CD127), IL‐2Rb (CD122), and CD62L." (PMID 39629989, 2025). "Timed administration of CD25-biased IL-2 treatment after RT favored intratumoral expansion of CD8+ T cells over regulatory T cells, which resulted in comparable anti-tumor effects as with RT plus IL-2Rβ (CD122)-biased IL-2 immunotherapy." (PMID 40502703, 2025). "In our scRNA-seq analysis of T cells from spontaneous murine tumor models, we found exhausted and regulatory-like T cells, including Cd8+Fgl2+Il2rb+ cells." (PMID 38888968, 2024). "A high level of IL2, IL2RA, and IL2RB gene expression and their relationships with tumor progression and malignancy have been previously reported." (PMID 33672900, 2021). "We have optimized digital pathology analysis of IL2RB IHC to further demonstrate its specific expression on a population of tumor infiltrating lymphocytes (TILs)." (PMID 33928242, 2021). "IL2RB activation via endogenous IL2 or biased therapeutic stimulation results in the expansion of anti-tumor immune cells, in particular CD8+, CD4+ and NK cells." (PMID 33928242, 2021). "We found significant associations between tumor mRNA expression of IL2RB and NOTCH1 genes and gender and between tumor mRNA expression of IL2RA and MAP2K1 genes and age." (PMID 33672900, 2021). "We performed a Welch’s T-test between IL2RB low and high groups (median split) in stromal regions (SR), invasive front (IF) and tumor body (TB) for CD3 and CD8 IHC-positive cells." (PMID 33928242, 2021). "To delineate the cellular origin of IL2RB expression, we interrogated publically available single-cell RNA-seq profiles from the CRC tumor and microenvironment of 11 patients and determined that IL2RB is predominantly expressed on a subset of T-cells." (PMID 33928242, 2021). "Although not significant, CD8 expression trended toward being higher in the IL2RB high tumor body group." (PMID 33928242, 2021). "The reduced antitumor activities to tumor growth at a secondary site in EKO mice were likely the combined effect of diminished memory T cells due to lower IL2rb and reduced tumor trafficking due to reduced expression of CXCR3." (PMID 33553191, 2021). "In addition, CLDN18 also correlated significantly with markers of activated CD8 + T cells such as MPZL1, CSE1L, CD37, AHSA1, CD3D and IL2RB, after adjusting for tumor purity." (PMID 37438735, 2023). "This analysis showed that genes representing T-cell activation and tumor-killing including Ifng, Vcam1, Rgs1, and Il2rb, had higher expression levels, whereas T-cell exhaustion genes such as Tim-3, Ccl3, Rgs2, and Cd6f3, had lower expression levels in Ogr1−/− mice than that in the WT mice." (PMID 34158625, 2021). "The microarray data revealed 728 distinctly regulated genes between two populations and the top highly expressed genes (IL2RB, GZMA, GZMB, EMR4, PRF1, CX3CR1, STAT1, and TLR9) in lung-derived Ly6C+ cells from EMT6 tumor-bearing mice are associated with effector T-cell function." (PMID 30926774, 2019). "In contrast, both FASLG and IL2RB were specifically expressed in T cells, and were highly correlated with T cell marker genes, suggesting that these two genes might assist in maintaining normal function of T cell-mediated immune response in tumor tissues." (PMID 35707353, 2022). "This signature includes key genes for maintaining cellular cytotoxicity such as ZNF683,41PRF1, IL2RB, and IFNG and immune activation and exhaustion markers including LAG3, PDCD1, PRF1, and TBX21 that contribute to anti-tumor immunity." (PMID 41045934, 2025). "We observed significant up-regulation of IL-15 signaling genes in tumor-infiltrating NK clusters, including IL15, IL2RB, IL2RG, STAT5B, and JAK1." (PMID 40315330, 2025).
tumor (continued). "Above results we noticed that IL4R, IL2RB and NAT2, which were differentially expressed in CRC tumor, significantly affect both pathological stages and prognosis of CRC patients, collectively." (PMID 35698180, 2022). "IL-15 is a potent stimulator of CD8+ T cells and NK cells via the activation of IL-15Rα, IL-2Rβ (also named CD122), and IL-2Rγ (also named CD132), which share receptors with IL-2, IL-4, IL-7, IL-9, and IL-21, and thereby reduces tumor burden." (PMID 36439125, 2022). "Next, we demonstrated that MSI-H CRC patients with increased IL2RB+ immune cells have an increased abundance of CD3, CD4 and FOXP3 TILs and higher PDL1 tumor and ICOS expression." (PMID 33928242, 2021). "Using the same 43rd percentile split established for IL2RB expression in the transcriptomics analysis, we observed a trend toward increased PDL1 tumor (P = 0.058) and ICOS expression (P = 0.1956) in the IL2RBHi patients." (PMID 33928242, 2021). "The C4 subset was annotated as Treg cells based on the high expression signature genes of tumor-infiltrating Tregs (FOXP3, IL2RA, IL2RB, IL2RG, IL10RA, MAGEH1, LAYN, and GATA3)." (PMID 34663810, 2021). "Administration of the CD122 (IL-2Rβ) IL2 pathway agonist bempegaldesleukin (known as NKTR-214), together with anti-PD-1, to B2M-knockout mice, markedly suppressed tumor growth and significantly increased mouse survival." (PMID 33276569, 2020). "These pathways were all connected to tumor growth, and the PI3K/Akt signaling pathway (eight involved genes: CCND2, CDKN1B, CSF1, EFNA3, FGFR2, FGFR3, IL2RB, and ITGA9) ranked first among upregulated pathways (Enrichment Score = 3.159187)." (PMID 30755239, 2019). "In the viral cytokine receptor pathway, upregulated genes (p = 1.39 × 10−5), including TNFRSF1A, CCL21, IL2RB, IL22RA1, and XCR1, suggest that oncolytic viruses exploit tumor-specific immune evasion mechanisms to selectively lyse tumor cells, activating anti-tumor immunity via DAMPs and PAMPs." (PMID 40406701, 2025). "Additional chemokines and growth factors, such as TGF‐α, CCL4, CCL20, IL‐17A, IL‐2RB, and FGF‐23, further underscore the multifaceted interplay between inflammation and tumor biology through pathways ranging from proliferation and angiogenesis to immune cell recruitment." (PMID 41458898, 2025). "To ensure our sorting purity, we compared tumor-infiltrating NK and T cell gene expression, highlighting unequivocal differences in DGE of canonical NK and T cell genes among the respective subsets, specifically NCAM1 and IL2Rb in NK cells, and CD3, CD8 and CD28 in T cells." (PMID 35874727, 2022). "The IL2RB-biased engineered cytokine NKTR-214 significantly increases the ratio of CD8 CTLs to immunosuppressive CD4 FOXP3 T-regulatory cells, creating a potent anti-tumor environment, while also increasing the expression of immune-checkpoints such as CD274 (PDL1)." (PMID 33928242, 2021). "To further assess the impact of CD56 on NK cell identification in lung tumors, we sorted tumor infiltrated cells into CD45- (not leukocyte cells) and CD45+ CD3- and with flow cytometry we analyzed the canonical CD16/CD56 combination, the CD122/CD94 (KLRD1/IL2RB) new marker pair or solely CD56." (PMID 41413116, 2025).
cancer (34 papers, 2010 to 2025). A tumor composed of atypical neoplastic, often pleomorphic cells that invade other tissues. "We selected those genes with functions known to be associated with cancer of which there were 12—SNVs: NOTCH2, PIK3CG, IL2RB, BAI3, FREM2 and RERE; indels: UTRN, CDHR3, NCOA5, CABYR, HOTAIR and FOLH1." (PMID 26017033, 2015). "LILRB4 was highly correlated with IL12RB1 and IL2RB across the various cancer types." (PMID 33974041, 2021). "However, research on IL2RB and cancer treatment remains relatively limited." (PMID 40072746, 2025). "Analysis of cluster-specific genes indicates that these clusters correspond to cancer cells (GFP, Crabp1, Ank), myeloid cells (Aif1, Ctsc, Mpeg1), lymphoid cells (Il2rb, Cd28, Cd3e/g/d, Cd37), and stromal cells (Col1a1/2, Lum, Eln, Dpt), respectively." (PMID 41280683, 2025). "Many of these genes function in inflammation (CXCR3, EOMES, IL18R1, GZMM, IL2rb), metastases (CXCR3, BUB1), poor outcome cancers (EOMES, BUB1), or stem cells (EOMES, BUB1)." (PMID 22053823, 2011). "Additionally, IL2RB, CD3E, and TBX21 showed significant enrichment in transcriptional misregulation in cancers and Th1 and Th2 cell differentiation pathways." (PMID 39974584, 2025). "In the process of module analysis and characteristic molecular screening, we selected two characteristic modules and 10 characteristic molecules (PTPRC, CD2, CD69, IRF8, CCR7, CCL5, il2rb, CXCL10, CCR5, TBX21), which could be used as biomarkers of cancer stem-like cells for GIST patients." (PMID 34925310, 2021). "Although the other two genes in the 3-ceRNA signatures, IRF4 and IL2RB, are not yet functionally characterized in GBM, they play essential roles in immune responses and cancer." (PMID 28241741, 2017).
infection (21 papers, 2009 to 2026). The state of being infected such as from the introduction of a foreign agent such as serum, vaccine, antigenic substance or organism. "Interestingly, the IL2RB was phosphorylated throughout the 24 hr initial infection period." (PMID 35846741, 2022). "While these population-level effects are strong, data at the single-cell level indicate that subsets of EBV-infected cells in both early infection and LCLs retain or upregulate DZ mRNA for CXCR4, FOXO1, AICDA, IL2RB, AURKC, and LMO2." (PMID 38059622, 2024). "Infection with UT127 led to the expression of the M1 markers IL12RB, IL2RB, and IFNG, concomitantly expressing the M2 markers CTLA4, IL10, and PLXNB2." (PMID 35163725, 2022). "However, the increase in these biomarkers did not persist at month 6 of the post-infection period, and instead, we saw significantly lower levels in four inflammatory biomarkers (IL2RB, LAPTGFbeta1, MCP2, and MCP4) in LC patients." (PMID 40572685, 2025).
immune disease (6 papers, 2018 to 2022). "The deletion of Il2rb causes mice to develop immune disease and NK cell dysfunction, including severe autoimmunity." (PMID 31949263, 2020). "In summary, KD's occurrence and development are significantly correlated with immune dysfunction—a decrease in the number of resting CD4+ memory T cells, which was caused mainly by the upregulated expression of IL2RB." (PMID 35924269, 2022). "IL2RB is a key point in T cell-mediated immune responses, and it can be saw in variety of immune diseases." (PMID 36458298, 2022). "DEGs that enriched to “immune system diseases” played critical roles in cell-matrix communication (THY1, LVRN, LUM, TIMP3, SPOCK1, LGALS3BP, FAT2, and SERPINE2) as well as inflammation (IL1R2, CD22, PTGES, TNFSF10, IL2RB, C3, SERPING1, and IL-17RE)." (PMID 30131724, 2018).
hematologic cancers (1 paper, 2019). "Many CIS occurred near genes implicated in hematologic cancers and hematopoietic development (Erg, Ets1, Epo, Il2rb, Flt3, Kras, Stat5b, Fli1)." (PMID 30940846, 2019).
IL2RB also shares sentences with these, for which no sentence is quoted: vitiligo (18 papers); influenza (4); Stroke (4); diabetes (3); hepatocellular carcinoma (3); psoriasis (3); acute lung injury (2); bacterial infection (2); experimental autoimmune encephalomyelitis (2); intrauterine growth restriction (2); ischemic stroke (2); lupus (2); multiple sclerosis (2); pancreatic cancer (2); rheumatoid arthritis (2); type 1 diabetes (2); acute GVHD (1); adult T cell leukemia (1); airway hyperresponsiveness (1); Allergy (1); androgenetic alopecia (1); angioimmunoblastic T-cell lymphoma (1); arterial hypertension (1); autoimmune enteropathy (1); autoimmune hepatitis (1); autoimmune hyperthyroidism (1); autoimmune thyroiditis (1); B cell lymphomas (1); basal cell carcinoma (1); benign ovarian tumor (1).
A further 48 diseases each share a sentence with IL2RB in 1 paper.